MSLN (mesothelin)
Diseases named in the same sentence as MSLN in open-access papers (continued):
Sharing a sentence is not in itself a finding about the gene and the disease.
cancer (continued). "In addition, MSLN protects cells from drug-induced apoptosis and mediates drug resistance in cancer 58,59,60." (PMID 33613114, 2021). "In summary, numerous important cancer types with high-level MSLN expression might benefit from future anti-MSLN therapies, but MSLN’s prognostic relevance appears to be limited." (PMID 33917081, 2021). "Mesothelin (MSLN) represents an attractive molecule for targeted cancer therapies." (PMID 33917081, 2021). "The successful analysis of more than 12,000 tumors identified various cancer types that might be particularly well suited for anti-MSLN drugs." (PMID 33917081, 2021). "Further research is needed in other types of cancer cells that highly express mesothelin." (PMID 33637083, 2021). "Next, we asked whether the improved affinity of SS1 to MSLN, compared to SS scFv, could have enhanced the ability of the corresponding virus to infect cancer cells." (PMID 33418877, 2021). "Using the peritoneal dissemination model, we demonstrated that several proteins related to proliferation, cancer stemness and chemoresistance were suppressed in the cancer cell clusters (which we named sherbet-like aggregates) that were blocked to attach to peritoneum by mesothelin blockage." (PMID 33637083, 2021). "Therefore, and due to its membranous location, MSLN represents an attractive molecule for target-specific cancer therapies." (PMID 33917081, 2021). "In relation to cancer, MSLN is overexpressed not only in CRC, but also in pancreatic, ovarian, lung, gastric, cervical, endometrial and biliary cancers, malignant pleural mesothelioma, uterine serous carcinoma, cholangiocarcinoma and paediatric acute myeloid leukaemia." (PMID 34769211, 2021). "Serum MSLN is used as a screening biomarker for cancer patients and to monitor responses." (PMID 33262421, 2020). "In addition, MSLN enables cancer cell survival, despite inflammation, due to resisting TNF-α-induced apoptosis, through elevating Akt/PI3K/NF-kB and IL-6/MCL-1 axes." (PMID 33344222, 2020). "However, even in malignant tumors of the same entity the level of Mesothelin expression varies between individuals, hence it can be expected that the response to Mesothelin-targeting therapies will be variable as well." (PMID 32815024, 2020). "Cancer cell lines with higher levels of MSLN indeed showed a trend toward higher levels of RARG." (PMID 32616712, 2020). "Moreover, we also observed smaller survival differences between high and low groups based on cancer-cell intrinsic expression of MSLN compared to bulk expression levels of MSLN." (PMID 32616712, 2020). "Although the physiological function of MSLN, as well as its role in cancer, are still unclear, it was originally suggested that MSLN could have a role in cell adhesion." (PMID 32612258, 2020). "In addition, we have recently shown that MSLN promotes peritoneal carcinomatosis of PDA by positively regulating several processes including cancer cell invasion." (PMID 32780245, 2020). "Consequently, the tight interaction of MSLN and MUC16 facilitates cancer cell attachment to MSLN-expressing serosal surfaces, leading to OC cell peritoneal implantation." (PMID 32983962, 2020). "Furthermore, the homogeneity of MSLN expression was reconfirmed by comparing the expression in the biopsy tissue with that in the invasive frontal margin of the cancer." (PMID 33196692, 2020). "For stage II/III CRC, we previously demonstrated that MSLN expression is a robust independent prognostic factor using standard sections, which were the maximum sections that included the invasive margin of the cancer." (PMID 33196692, 2020). "Among these tracks, mesothelin has recently emerged as a “hot prospect” because of its restricted expression on mesothelial cells in healthy tissues and its over-expression in several aggressive cancers and notably in 30–70% of TNBC." (PMID 31354732, 2019). "In contrast, the aberrant overexpression of MSLN is observed in various cancer cells." (PMID 31463062, 2019).
cancer (continued). "Yet, in cancer cells, MSLN is overexpressed on nearly a third of human malignancies." (PMID 30031396, 2018). "However, the expression levels varied among the surgical specimens, even within the same histological tumors, and moreover the mixtures of the cancer cells with varying expression of MSLN were observed in same sample." (PMID 30558663, 2018). "However, the expression and biological functions of mesothelin in cancer progression remain poorly understood." (PMID 30140382, 2018). "Mesothelin expression is mostly restricted to tumors in adult mammals and thus may be a good target for cancer treatment." (PMID 29474384, 2018). "Furthermore, mesothelin-directed chimeric antigen receptors (CAR) are also in clinical trials for various cancers." (PMID 29854291, 2018). "Following stimulation with mesothelin expressing cancer cells, chimeric antigen receptor T cells were dose-dependently activated; this activation was enhanced by co-culture with invariant natural killer T cells and subsequently abrogated by treatment with anti-interferon-γ antibodies." (PMID 30558663, 2018). "MSLN is a glycosyl-phosphatidylinositol- (GPI-) linked membrane glycoprotein, which is highly expressed in mesothelioma, pancreatic, lung, ovarian, and other cancers, but lowly expressed in normal tissue." (PMID 29707526, 2018). "RG7787 binds to MSLN on the cancer cell surface, is internalized by endocytosis, undergoes retrograde transport to the endoplasmic reticulum and then is released into the cytosol by an unknown mechanism." (PMID 27999204, 2017). "The anti-MSLN targeting domain binds to the surface of cancer cells, triggering internalization." (PMID 27999204, 2017). "For instance, mesothelin was reported as a potential immunotherapeutic target in various cancers." (PMID 28218682, 2017). "Despite extensive studies of MSLN as a potential diagnostic and therapeutic target, neither the physiologic role of MSLN nor its pathological mechanism in cancer is well defined." (PMID 28288645, 2017). "Neither overexpression of other cancer-associated antigens nor correlative expressions between those antigens and MSLN have been fully investigated." (PMID 29100432, 2017). "Mesothelin interacts with CA125/MUC16 ovarian cancer antigen, and this interaction has been hypothesized to play a role in metastasis of ovarian cancers." (PMID 26931187, 2016). "As seen with Ezrin and Mesothelin, ENOA has been linked to cell migration and cancer metastasis." (PMID 26840568, 2016). "Additionally, its identification as a cancer cell antigen has helped mesothelin emerge as a target for antibody-based therapies." (PMID 26981775, 2016). "Thus, the fact that mesothelin is expressed on some aggressive cancers and that there is limited normal expression of mesothelin gives impetus to the development of antibodies targeting the mesothelin antigen." (PMID 26981775, 2016). "We have shown that mouse mesothelin also has similar expression to human mesothelin, that it is restricted to certain organs and cancer and embryonic cells, and that murine mesothelin is expressed on the cell surface as well as released into supernatants, similar to human cells." (PMID 26931187, 2016). "However we found for the mouse, as in humans, mesothelin protein expression was largely confined to certain cancers." (PMID 26931187, 2016). "For potential cancer therapy, we tested immunotoxins targeting different epitopes, and showed that the cell surface mesothelin expression level and immunotoxin binding affinity were two major factors that determine the response of most cancer cell lines in vitro." (PMID 25996440, 2015). "Recent studies highlighted the possible mechanisms by which MSLN could play an active role in cancer progression; it was shown to interact with MUC16, and to activate the p38 pathway, leading to the selective induction of matrix metalloproteinase (MMP)-7." (PMID 24465798, 2014).
cancer (continued). "MSLN could also increase cancer cell survival and proliferation via the activation of the NF-κB signaling pathway." (PMID 24465798, 2014). "Here, we aimed to assess naturally occurring T cell responses to MSLN in cancer and benign pancreatic disease patients and establish whether there is any possible association between MSLN-T cell responses and the levels of plasma MSLN or cytokines." (PMID 24520352, 2014). "However, the mean concentration of MSLN identified in the cancer group was higher than in the benign disease groups." (PMID 24520352, 2014). "On the cancer biology level, calretinin has higher positive rates in CC than mesothelin (52.17% versus 33%), and may also be a more sensitive and/or specific therapeutic target for CC." (PMID 24860692, 2014). "Interestingly, in our series, the use of strict criteria of MSLN- positivity identified carcinomas with significantly worse clinical behavior." (PMID 25506917, 2014). "IL12-SS1 (Fv) is the first reported immunocytokine to mesothelin-positive tumors and may be an attractive addition to mesothelin-targeted cancer therapies." (PMID 24260587, 2013). "Mesothelin is a particularly promising cancer vaccine target owing to its low level of expression in nontumor tissues and high levels of expression in pancreatic as well as other cancers (i.e., ovarian)." (PMID 23509731, 2013). "Based on these findings, the authors suggested that there may be an important role for CA125 and MSLN in the metastatic spread of cancer." (PMID 22485139, 2012). "Furthermore, promoter-driven cancer gene therapy which exploits overactive MUC1 and MSLN promoters in various cancer types has been extensively studied in pre-clinical cancer models using viral vectors." (PMID 22792233, 2012). "This differential expression of mesothelin makes it an attractive target for cancer therapy." (PMID 23034174, 2012). "Cancer cells overexpressing mesothelin demonstrated enhanced migration and metastasis." (PMID 23319948, 2012). "CK5/6 and mesothelin are often expressed in lung and other cancers." (PMID 22768319, 2012). "Calretinin, CK 5/6, podoplanin, or mesothelin was often expressed in other cancers." (PMID 22768319, 2012). "In addition to the translational ramifications of such investigations, the information obtained is useful for evaluating the role of MSLN in cancer biology." (PMID 22485139, 2012). "However, despite some progress, the role of mesothelin during cancer development remains to be fully understood." (PMID 22163010, 2011). "Mesothelin expression in human cancers has been studied extensively." (PMID 21801396, 2011). "Although the biological function of mesothelin remains unclear, mesothelin's limited expression in normal tissue and high expression in various cancers make it an attractive candidate for immunotherapy." (PMID 21305058, 2011). "Mesothelin, calretinin and WT-1 were expressed in almost all cancer cells." (PMID 21305058, 2011). "Our study delineates a MSLN-Akt-NF-κB-IL-6-Mcl-1 survival axis that may be operative in PC cells, and might help cancer cells' survival in the highly inflammatory milieu evident in PC." (PMID 21880146, 2011). "Although the biological functions of mesothelin remain largely unknown, there is evidence that mesothelin has the potential as a new cancer biomarker and as a target molecule for gene therapy." (PMID 19293794, 2009). "Mesothelin mRNA has previously been described as overexpressed in ovarian and mesothelioma cancer tissues, and the gene product is referred to a marker of these two cancers." (PMID 16421595, 2006). "However, in cancers, mesothelin is often overexpressed, leading to the downregulation of miR-198." (PMID 40227616, 2025). "Additionally, high co-expression of HAVCR2 and MSLN have been shown to be prevalent in several cancers and may also be vulnerable to the use of CAR-T therapies." (PMID 39174744, 2024).
cancer (continued). "Because MSLN is often expressed on the surface of human normal tissues and its nonspecific toxicity is lower, researchers have designed a variety of therapeutic methods targeting MSLN antigens, such as antitoxins, antibody-based therapy, cancer vaccines and adoptive T-cell therapy." (PMID 36979400, 2023). "As the antigens targeted by CARs can serve as critical signaling molecules in cancer cells (e.g., mesothelin in solid tumors or BCMA in plasma cells), the capture of target-associated molecules by NK or T cells via trogocytosis may potentially modify the cellular function of CAR-expressing cells." (PMID 37974170, 2023). "Hence, MSLN has been found to be an attractive target for use in cancer treatment." (PMID 36434635, 2022). "In summary, MSLN-targeted CAR-T cells could be feasible for MSLN-positive cancers, such as NSCLC." (PMID 34790207, 2021). "Thus, MSLN has become a unique biomarker for targeting cancer therapy." (PMID 34577541, 2021). "Clinical significances of mesothelin might be different among several carcinomas." (PMID 33832498, 2021). "Moreover, MSLN is highly expressed in several malignant tumors, and its expression, which is reportedly related to the Wnt signaling pathway, might be associated with patient prognosis." (PMID 33196692, 2020). "For example, a sample with higher bulk expression of MSLN may either contain cancer cells with higher intrinsic expression of MSLN or the expression of MSLN may be constant and the sample may just have higher purity (proportion of cancer cells), resulting in higher bulk expression of the gene." (PMID 32616712, 2020). "The causes of MSLN overexpression in cancer are not clear but could be related to the hypomethylation of MSLN gene or the deregulation of the Wnt signaling pathways." (PMID 31354732, 2019). "Thus, MSLN is an ideal cancer antigen for targeted immunotherapy." (PMID 31209210, 2019). "Mesothelin may therefore be an effective target for cancer immunotherapy." (PMID 29568387, 2018). "The use of MSLN as a plasma biomarker has been investigated by several groups using blood ELISA tests and demonstrated that serum MSLN levels decrease after surgical therapy and, therefore, may be useful in monitoring treatment response in MSLN expression cancers." (PMID 30134520, 2018). "Moreover, it has been reported that MSLN could have a driving role in cancer by regulating cell proliferation and invasiveness." (PMID 28125734, 2017). "Mesothelin is a tumor differentiation antigen (40 kDa) that is normally present on the mesothelial cells of pleura, peritoneum, and pericardium and is highly expressed in many human cancers, including malignant mesothelioma, pancreatic, ovarian, and lung adenocarcinoma." (PMID 29312333, 2017). "MSLN may also promote cancer cell survival and proliferation via the NF-κB signaling pathway." (PMID 25883990, 2015). "However, our data suggested that circulating IL-10 and MSLN levels may undergo quantitative change when malignancy had developed compared to normal status." (PMID 24520352, 2014). "Furthermore, the binding of MTBHsp70 to cancer cells cannot be blocked by recombinant MSLN." (PMID 24565018, 2014). "This was confirmed by a pan-cancer analysis of the TCGA cohort to evaluate the MSLN and CD47 mRNA expression levels across 30 cancer entities." (PMID 40402266, 2025). "Several clinical trials are already evaluating mesothelin-targeted CAR-T cells (known as meso-CAR-T, CART-meso or anti-MSLN CAR-T cells) in various cancer types." (PMID 40427042, 2025). "Another piece of evidence supporting the relationship between MSLN and MMP-7 and their involvement in cancer metastasis comes from a study conducted on NSCLC." (PMID 41335396, 2025). "MSLN interacts through the hormone RARG and tyrosine TNK2 to trigger AKT, owing to an in-silico strategy that used the cancer genome atlas (TCGA)." (PMID 40227616, 2025).
cancer (continued). "Clinical trials using anti-mesothelin CAR T cells, or mesoCAR T cells, are being conducted in a number of cancer types, including EOC." (PMID 40649775, 2025). "MSLN overexpression enhances resistance to the chemotherapeutic drug gemcitabine since it promotes the EMT and characteristics found in cancer stem cells." (PMID 40227616, 2025). "Their downregulation suggests a novel mechanism of action of MSLN targeting agents, potentially involving EMT modulation and suppression of cancer progression." (PMID 41335396, 2025). "In the context of cancer biomarkers, proteins such as CA125/MUC16, Mesothelin and Enolase 2 are increasingly used not only for diagnosis and monitoring, but also as targets to evaluate therapeutic impact and prognosis in oncology." (PMID 41515404, 2025). "This study focuses on the protein mesothelin (MSLN), which is highly expressed in over 89% of clinical PDAC specimens and helps cancer cells grow and avoid death." (PMID 40563707, 2025). "Several studies have reported an interaction between MSLN and CA125, an antigen expressed in various cancers as well as in normal peritoneal tissue." (PMID 41335396, 2025). "Consistently with its functional role and further reinforcing its association with MSLN, elevated MMP-7 expression has been reported across several MSLN-positive malignancies, including pancreatic, breast, colorectal, ovarian, and NSCL cancers." (PMID 41335396, 2025). "Mesothelin (MSLN) promotes the level and activation of MET through the JNK signaling pathway, enabling cancer cells to disrupt tight junctions and the integrity of the blood-brain barrier (BBB), thus penetrating the barrier." (PMID 39712244, 2024). "Our focus was on elucidating the subtypes of these MSLN/NCL-specific T cells and evaluating their anti-cancer efficacy." (PMID 39294656, 2024). "Mesothelin is overexpressed in solid tumors and plays a role in activating Akt/PI3K and mTOR signaling pathways, thereby promoting cancer cell proliferation and survival." (PMID 38396817, 2024). "Of these, ALDOB, WNT11, MSLN, RAC3, and IL1RN have known roles in CRC, FBLX16 has known roles in other cancers, and SLC38A11 and WBSCR27 are relatively uncharacterized." (PMID 38680862, 2024). "Some studies suggested that surface molecules such as mesothelin (MSLN) and tissue factor (TF) are highly expressed in TNBC cancer cells and can also be a potential targeted surface molecule for TNBC therapy." (PMID 38694508, 2024). "Because of the differential expression of several antigens (e.g., CD19, BCMA, GD2, GPC3, and mesothelin) on certain cancer cells, CAR-engineered T (CAR-T) cells specific for these antigens have exhibited great potential in cancer immunotherapies." (PMID 36463401, 2023). "DNA methylation had a moderate contribution for the two newly predicted cancer genes, COL5A1 and MSLN." (PMID 37862225, 2023). "Mesothelin (MSLN) and C-XC chemokine receptor 4 (CXCR4) are membrane-bound proteins, expressed in certain cancers, and thus are promising targets for endo-radiotherapy." (PMID 37047331, 2023). "Since MSLN is a highly specific antigen in several cancers, CAR-T therapy has been shown to be a promising strategy for the treatment of these cancers." (PMID 37359558, 2023). "FAP is highly expressed in stroma of most carcinomas, including PDAC9, and mesothelin is a promising TAA target expressed at high levels in PDAC 24,26." (PMID 37607999, 2023). "In vitro studies indicate that amatuximab inhibits mesothelin interaction with CA125/MUC16 and such a blockage reduces the cancer’s ability to metastasize and invade into other tissues." (PMID 35326701, 2022). "Mesothelin mediates cellular adhesion through binding to MUC16, while in cancer it is involved in resistance to cell death, cell proliferation, invasive and metastatic potential, angiogenesis, apoptosis regulation and epithelial-to-mesenchymal transition." (PMID 36009489, 2022).